IL6 (interleukin 6)
Diseases named in the same sentence as IL6 in open-access papers (continued):
Sharing a sentence is not in itself a finding about the gene and the disease.
hepatocellular carcinoma (continued). "In addition, IL-6 antagonizes TGF-β-induced apoptosis in human hepatoma cell line Hep3B, and this could be critical during cirrhosis favoring the transformation of hepatocytes parallel to the development of liver fibrosis." (PMID 22032643, 2011). "During IL6-induced JAK1 signaling in tumor cells, we identified a novel phosphorylation site of ACAP4 at Tyr843 that facilitates hepatoma cell migration by increasing ARF6-GTPase activity." (PMID 39744421, 2025). "Indeed, the IL-4, IL-6, and IL-10 levels were found to be higher in patients with ascites and hepatocellular carcinoma (HCC) than patients with cirrhosis alone." (PMID 40149656, 2025). "Liver KCs are polarized to TAMs by the induction of hepatoma cell-derived exosomes, which then secrete IL6 and activate JAK1 in hepatoma cells." (PMID 39744421, 2025). "Since increased levels of IL-6 in the tumor site or plasma are associated with a worse prognosis for patients with advanced hepatocellular carcinoma (HCC), inhibiting the IL-6 pathway may enhance current HCC therapeutic approaches." (PMID 39062019, 2024). "A notable increase in the expression of IL-6 in Hepatocellular carcinoma (HCC) cells was observed in our previous research, indicating that the administration of BEZ235 could potentially induce an inflammatory response within the body." (PMID 38564670, 2024). "In hepatocellular carcinoma (HCC), TAMs facilitate the expansion of cancer cells by secreting IL-6 activating STAT3." (PMID 36260158, 2023). "Hepatocellular carcinoma (HCC), the most common primary liver cancer, prevails mainly in males and has long been attributed to androgens and higher circumstantial levels of interleukin-6 (IL-6) produced by resident hepatic macrophages." (PMID 37752418, 2023). "In hepatocellular carcinoma (HCC), IL-6 exhibits a dual role, with its effects being contingent upon its context." (PMID 37892997, 2023). "In gastric cancer and hepatocellular carcinoma, AOC1 functions as an oncogene, either by activating the AKT signaling pathway and EMT or by regulating the IL-6/JAK/STAT3 pathway." (PMID 37525249, 2023). "For instance, in the Hepa1-6 hepatocellular carcinoma model, CCRK is necessary for IL-6 expression which led to the expansion of MDSCs in peripheral blood." (PMID 38188300, 2023). "It promotes IL6 expression, and IL-6 promotes STAT3 phosphorylation, which activates the IL-6/STAT3 pathway and thus enhances the proliferation of hepatocellular carcinoma cells." (PMID 37680619, 2023). "In hepatocellular carcinoma, as a ceRNA, DLGAP1-AS1 elevates the level of the carcinogenic cytokine IL-6 by sponging miR-26a/b-5p and activating the Wnt/β-catenin pathway." (PMID 35113786, 2022). "In hepatocellular carcinoma, CnP inhibits the expression of α-SMA, the activation marker of CAFs, and the tumor-promoting cytokine production such as IL-6, IL-8, and CCL-2 of CAFs." (PMID 35327514, 2022). "By activating STAT3, TAM-derived IL-6 promotes hepatocellular carcinoma (HCC) development." (PMID 36679900, 2022). "Additionally, the sex-biased phenotype of certain cancers [e.g., hepatocellular carcinoma (HCC) which is 3-5-fold more common in men] was related to the inhibition of macrophage-derived IL-6 production by estradiol-17β (E2)." (PMID 35406728, 2022). "The ability of E2 to inhibit IL-6 production accounts for this sex-specific phenotype in the human disease and the DEN-induced mouse model of hepatocellular carcinoma." (PMID 35406728, 2022). "IL-6 and IL-1 have been reported to enhance PAI-1 transcription in hepatoma cell lines and whereas IL-6 induced a modest increase in PAI-1 mRNA levels, IL-6 in combination with IL-1 had a much greater effect on PAI-1 mRNA expression." (PMID 35883605, 2022). "In this sense, sympathetic denervation or blocking α1-ARs in KCs reduces the production of cytokines, such as IL-6 and TGF-β, and reduces the development of HCC (hepatocellular carcinoma)." (PMID 35954171, 2022).
hepatocellular carcinoma (continued). "IL-6 has been studied extensively in VM promotion and crosslinked to STAT3 in human hepatocellular carcinoma." (PMID 34055597, 2021). "The cytokines like TNF-α and IL-6 and their downstream targets nuclear factor κB (NF-κB) c-Jun N-terminal kinase and STAT3 drive inflammation-related hepatocellular carcinoma." (PMID 34194957, 2021). "Similarly, chemerin was found to counteract tumor progression in hepatocellular carcinoma (HCC) by suppressing IL-6 and GM-CSF expression." (PMID 35008289, 2021). "Treatment of hepatoma cells or primary murine hepatocytes with BMP6, BMP2 or IL-6 recapitulates hepcidin induction." (PMID 34161397, 2021). "CAF-derived cytokines, such as IL-6 and SDF-1α, can induce MDSC generation and activation and impair human anti-tumor immune responses to promote hepatocellular carcinoma progression." (PMID 34305902, 2021). "In mice, while only a small fraction of BM HSPCs expressed GM-CSF, IL-6, or TNF-α, approximately 40% of splenic LSK cells, both in tumor-free and orthotopic hepatoma-bearing mice, expressed TNF-α, suggesting niche-dependent functional heterogeneity." (PMID 33936078, 2021). "IL-6 can activate STAT3 signal pathway to drive hepatocyte replication and promote the occurrence of hepatocellular carcinoma." (PMID 35096588, 2021). "We have previously reported the role of the transcriptional factor NF-E2-related factor 2 (Nrf2) in cancer-TAM interactions in hepatocellular carcinoma (HCC) and pancreatic cancer and cancer-CAF interactions through IL-6 and CXCL10 in pancreatic cancer." (PMID 33659044, 2021). "In malignant melanoma, squamous cell carcinoma (SCC), hepatocellular carcinoma (HCC), ovarian and bladder cancers, the expression levels of IL-6 were found to be positively correlated with the number of MDSC." (PMID 34975496, 2021). "In hepatocellular carcinoma, human CAFs can attract monocytes by the SDF-1a/CXCR4 pathway and facilitate their differentiation into MDSCs via IL-6-mediated STAT3 activation." (PMID 34336660, 2021). "For example, a responsive cytokine of the IL-6/STAT3 signalling pathway, IL-23 has been reported to promote the malignant properties of hepatoma cells." (PMID 34078370, 2021). "The hepatoma cell line Hepa-1c1c7 (ATCC® CRL-2026TM) exposed to palmitate presented increased JNK phosphorylation, IL-6 and TNF-α mRNA compared to cells exposed to vehicle solvent alone." (PMID 31913329, 2020). "In particular, high secretion of IL6 in MSCs can activate the IL6/STAT3 signaling pathway and promote cell invasion in hepatocellular carcinoma cells." (PMID 32560387, 2020). "Like IL-6 related markers and chemokines/cytokines, KI67 and Cyclin D1 dysregulation is an indicator of many different liver conditions including hepatocellular carcinoma, nonalcoholic fatty liver disease, chronic alcohol exposure, and liver injury." (PMID 33250767, 2020). "C/EBPβ was originally identified as nuclear factor interleukin-6 (NFIL6) because of its inducibility by IL-6 and its important role in the activation of acute inflammatory response genes in human hepatoma cells." (PMID 32660130, 2020). "More recently, IL-6/JAK1-mediated STAT3 phosphorylation was found to promote the transcription of DNMT3B and OCT4 in hepatocellular carcinoma cells, which can further up-regulate the transcription of DNMT156." (PMID 32895373, 2020). "IL-6 is positively correlated with PD-L1 expression in human hepatocellular carcinoma (HCC) cells, and IL-6 induces PD-L1 stability through glycosylation in a HCC cell line." (PMID 32403421, 2020). "Furthermore, in hepatocellular carcinoma (HCC), CAFs secrete high levels of IL-6, which promoted stem cell-like properties in HCC cells by activating Notch 1 signalling through STAT3 Tyr705 phosphorylation." (PMID 32575680, 2020).
hepatocellular carcinoma (continued). "MiR-589-5p promotes the spheroid formation of CD133+ hepatocellular carcinoma (HCC) cells and their tumorigenicity in vivo by targeting the IL-6 pathway inhibitors SOCS2/5 and PTPNI/11, while it further accelerates tumor chemoresistance via regulation of Stat3 signaling." (PMID 32932969, 2020). "Nanocapsulated quercetin significantly reduced the incidence of hepatocellular carcinoma in rats and decreased the production of TNF-α and IL-6 in liver induced by diethyl nitrosamine." (PMID 33425996, 2020). "Importantly, this pathway may not be specific to pancreatic cancer: CAFs isolated from human hepatocellular carcinomas were capable of driving an immunosuppressive gene signature and functions in monocytes and in neutrophils via IL-6 mediated activation of STAT3 signaling." (PMID 31428105, 2019). "In hepatocellular carcinoma cells, NCTD reversed IL-6-induced epithelial-mesenchymal transition process and inhibited STAT3 phosphorylation like JSI-124, a selective inhibitor of STAT3." (PMID 31315217, 2019). "High serum levels of IL6, an inflammatory cytokine, can predict the development of hepatitis B virus (HBV)-infected hepatocellular carcinoma (HBV-HCC)." (PMID 31505803, 2019). "The effect of factors known to regulate TMPRSS6 expression, such as IL‐6, LPS and BMP‐6,39, 42 should be taken into consideration in human hepatoma cell lines, but also in mice to see if they affect expression levels of specific TMPRSS6 isoforms." (PMID 29441715, 2018). "The quantitation of the bands indicates that IL-6 treatment increases C/EBP-β and -δ binding activity in Alexander human hepatoma cells." (PMID 29644527, 2018). "Since CRP is produced mainly in the liver in response to interleukin-6 (IL-6), we evaluated the effect of gemcabene on CRP production by cytokine-stimulated human hepatoma PLC/PRF/5 (Alexander) cells." (PMID 29644527, 2018). "Remarkably, miR-197 reduces STAT3 signaling via miR-197/IL-22/STAT3 and miR-197/IL-6/STAT3 pathways in human keratinocytes and hepatocellular carcinomas." (PMID 29890998, 2018). "Methylation silencing of SOCS3 increases the IL-6/JAK/STAT3 and FAK phosphorylation in human hepatocellular carcinoma." (PMID 28228755, 2017). "IL-17 increases IL-6 expression through the AKT pathway in hepatocellular carcinoma (HCC)." (PMID 28978186, 2017). "Human hepatoma cells and primary murine hepatocytes were treated with TNF-α/LPS/IL-6/IL-10 and USP18, phosphorylated (p)-STAT1 and myxovirus (influenza virus) resistance 1 (Mx1) expression was determined." (PMID 27009955, 2016). "Interleukin 6 (IL6), tumor necrosis factor α (TNFα) and TNF receptor-1(TNFR1) have been shown to involve in oval cell proliferation and hepatocellular carcinoma (HCC) development." (PMID 27556180, 2016). "This is consistent with higher proinflammatory cytokines (IL-1β, IL-6 and TNF) in hepatoma compared with healthy tissues." (PMID 27551463, 2015). "Using primary hepatocytes from mice and a hepatoma cell line, it was shown that BMP2, 4 and 9 can induce hepcidin transcription independently of Hfe, Tfr2 or Il6 (interleukin 6)." (PMID 26182354, 2015). "Subsequently, it was shown that human hepatoma cell lines, zebrafish and mice pre-treated with a BMP type I receptor inhibitor had a reduced hepcidin response to IL6 treatment." (PMID 26182354, 2015). "IL6 has been shown to suppress HBV replication and/or transcription in hepatoma cells, primary hepatocytes and HBV transgenic mice." (PMID 26580974, 2015). "Although, it is induced by IL-6, IL-1-β and TNF-α in hepatoma cells, and overexpressed in the liver of mice challenged by lipopolysaccharide rendering it as an acute phase protein, its real physiological functions has not been clarified so far." (PMID 24497876, 2014). "Subsequently IL-17F has successfully demonstrated direct inhibition of IL-6, IL-8, and VEGF expression of hepatocellular carcinoma (HCC) in vitro." (PMID 25110397, 2014).
hepatocellular carcinoma (continued). "In a study which introduced a mixture of IL-6, IL-1, and TNF-α in murine hepatoma cell line Hepa 1–6, a reduction in PON1 mRNA was observed." (PMID 24799979, 2014). "Serum ghrelin, tumour necrosis factor (TNF)-α and interleukin 6 (IL6) levels have been reported to be significantly higher in cirrhosis and hepatocellular carcinoma patients, whereas serum leptin levels were observed to be decreased." (PMID 24137355, 2013). "In liver disease, elevated IL-6 levels are seen in alcoholic cirrhosis, chronic hepatitis B, primary biliary cirrhosis, hepatitis C (HCV) cirrhosis, and hepatocellular carcinoma (HCC)." (PMID 22514624, 2012). "IL-6 has been shown to regulate (increase) CD14 expression and synthesis in both HepG2 hepatocellular carcinoma cells and in human primary hepatocytes." (PMID 22970235, 2012). "Accordingly, hepatoma cell line (Hep-G2), which expressed low levels of NNMT, increased NNMT expression several fold upon stimulation by IL-6." (PMID 19216803, 2009). "The level of serum IL-6 has been reported to be elevated in patients with CHB, cirrhosis and hepatocellular carcinoma, relative to normal subjects." (PMID 19374779, 2009). "CASC11 affects PD-L1 by activating NF-κB and PI3K/AKT/mTOR signaling through the EIF4A3/E2F1 pathway in hepatocellular carcinoma, while HOTTIP induces IL-6 production, activating the IL-6/JAK/STAT3/PD-L1 pathway in neutrophils within the ovarian cancer microenvironment." (PMID 41221298, 2025). "Furthermore, in hepatocellular carcinoma (HCC), IL‐6 derived from CAFs recruits neutrophils through the STAT3/PD‐L1 signaling pathway." (PMID 41164803, 2025). "IL6 then activates JAK1 to phosphorylate its downstream effector ACAP4 at Tyr843, a novel phosphorylation site identified in this context, which in turn promotes ARF6-GTPase activity and hepatoma cell migration." (PMID 39744421, 2025). "In addition, pharmacological inhibition of APE1’s redox function prevents the activation of NK-kB, IL-6, and IL-8 induced by THF-α and free fatty acids in the human hepatocellular carcinoma cell line JHH-6." (PMID 41463362, 2025). "In addition, consistent with our results, Bifidobacterium pseudolongum-generated acetate reached the liver via the portal vein, where it suppressed the IL-6/JAK1/STAT3 signaling pathway in hepatocytes, thereby preventing hepatocellular carcinoma." (PMID 40693815, 2025). "Similar effects were found in hepatic carcinoma and triple negative breast cancers, where CAF-induced IL-6 and CXXL12, respectively, accelerated M-MDSC accumulation in the TME, which resulted in reduced production of IFNγ with serious impediment to the growth of CTLs." (PMID 40805183, 2025). "It has been reported that DNMT3B may play a critical role in the IL-6-mediated OCT4 expression and the drug sensitivity of sorafenib-resistant hepatocellular carcinoma." (PMID 37934565, 2023). "For example, miR-20a-5p was downregulated during liver fibrosis and transfection of miR-20a-5p reduced the production of the proinflammatory cytokines IL-6, TNF-α, IL-18, and IFN-γ in a murine hepatoma cell line by targeting transforming growth factor beta 2 (TGFB2)." (PMID 36634655, 2023). "The ability of IL-6 to trigger an EMT and enhance cancer cell motility has been extended to colorectal cancer, cancer stem cells in blood vessels in head and neck squamous cell carcinomas, hepatocellular cancer, and laryngeal squamous cell carcinoma." (PMID 35406728, 2022). "Importantly, it has been reported that there is a positive feedback loop in the presence of chemotaxis between IL-6 and APOBEC3B in hepatoma cells, i.e., APOBEC3B promotes IL-6 to recruit MDSCs and TAMs to promote the development of liver cancer." (PMID 36203448, 2022). "Also, the activation of IL-6/JAK/STAT signaling is observed in steatohepatitis and hepatocellular carcinoma." (PMID 35464767, 2022).
hepatocellular carcinoma (continued). "IL-6 in particular has anti-apoptotic actions, through upregulation of Mcl-1 (a member of the Bcl-2 family) in a number of cancer cell lines (e.g. C33A, AGS), including prevention of apoptosis in hepatoma cells under the influence of TGFβ." (PMID 36038791, 2022). "TAMs activated STAT3 to produce IL-6 and induced an increase in the number of CD44+ hepatoma cells." (PMID 35740975, 2022). "DLGAP1-AS1 sequestered miR-486-5p to promote cell proliferation of hepatocellular cancer, and DLGAP1-AS1 urged the occurrence of liver cancer and epithelial-mesenchymal transition through the feedback loop of the miR-26a/b-5p/IL-6/JAK2/STAT3 and Wnt/β-catenin pathways." (PMID 35341001, 2022). "Moreover, in Hep3B hepatoma cells, inhibition of BMP signalling diminished the IL-6 mediated hepcidin induction suggesting that BMP/SMAD pathway regulates the IL-6 mediated JAK/STAT pathway." (PMID 33835366, 2021). "In hepatocellular carcinoma (HCC), CAFs that overexpress IL-6 can induce strong immunosuppression in the TME by recruiting immunosuppressive cells such as bone marrow-derived suppressor cells and can impair the function of tumor-infiltrating T cells by upregulating suppressive immune checkpoints." (PMID 35058933, 2021). "IL-6, regulated on activation normal T cell expressed and secreted (RANTES), and granulocyte colony-stimulating factor (G-CSF) in irradiated mouse plasma and hepatoma cell cultures were measured with ELISA kits." (PMID 32117702, 2020). "Similarly, patient-derived hepatocellular carcinoma CAFs were shown to upregulate the expression of PD-L1 on the surface of neutrophils, another prominent component of the TME, through secretion of IL-6 and activation of a STAT3-dependent signalling pathway." (PMID 32967079, 2020). "IL-6 induces human HO-1 gene expression via the JAK/STAT3 pathway in HepG2 cells; however, there is a negative autocrine between expressions of HO-1 and IL-6 in human hepatoma cells." (PMID 32204510, 2020). "The proinflammatory cytokines IL-1, IL-6, and Oncostatin M all significantly upregulated C4BP expressions in the HepG-2 hepatoma cell line, suggesting an interplay between inflammation-driven regulation of complement components shielding the tumor from cytotoxic effectors." (PMID 33718121, 2020). "Consistently, CCl4 treatment could up‐regulate the expression of RelB as well as inflammatory cytokines such as IL‐6 and TGF‐β1 in hepatoma cell as well as in WT mice." (PMID 32306539, 2020). "High levels of CAF‐secreted IL‐6 induced tumor immunosuppression by recruiting MDSCs and upregulating PD‐L1 expression, impairing the efficacy of anti‐PD‐L1 immunotherapy against hepatocellular carcinoma (HCC), and IL‐6 blockade increased the efficacy of PD‐L1 treatment." (PMID 31365790, 2019). "Last, a previous study showed that IL6 was not related to the clinical outcome in patients with resectable hepatocellular carcinoma, so our results need to be further validated in well-designed future studies." (PMID 31781194, 2019). "The enhancement of FGL1 levels was regulated by IL-6 and it participates in the development of non-alcoholic fatty liver disease, hepatocellular carcinomas, and hepatocyte mitogenic activity." (PMID 30406363, 2019). "We concluded from these experiments that IL-6 trans-signaling but not IL-6 classic signaling was involved in the development of hepatocellular carcinoma, at least in the diethylnitrosamine model." (PMID 31694340, 2019). "Human hepatoma Huh-7 cells transfected with an NS5A vector have demonstrated an elevation of ROS with resulting activation of NF-KB and STAT-3 pathways that then led to the release of various array of cytokines, including IL-6, IL-8, TNFα, and TGFβ." (PMID 31540136, 2019). "Similarly, PML is known to modulate interleukin (IL)-6-induced STAT3 activation and hepatoma cell growth by interacting with HDAC361." (PMID 30143675, 2018).